EGR1 (early growth response 1)
Diseases named in the same sentence as EGR1 in open-access papers (continued):
Sharing a sentence is not in itself a finding about the gene and the disease.
tumor (continued). "Various studies have indicated Egr-1 is involved in regulation of cell proliferation and may have tumor suppressive functions." (PMID 25029911, 2014). "In tumor cells, it can activate EGR1 to endorse cell survival." (PMID 25364730, 2014). "Gene expression analysis showed that several genes involved in tumor development and metastasis (EGR1, COX2, MALAT1, AKAP12, ADM) were similarly induced in CSC and cisplatin-resistant H460 cells, in agreement with a close similarity between these two cell populations." (PMID 24961511, 2014). "Interestingly, a recent study showed that the disruption of certain oncosupression transcriptors have been shown to induce both FOS and EGR1 expression in the early stages of tumor development." (PMID 24619124, 2014). "Several of the genes differentially regulated are associated with tumor initiation (e.g., AhR, CYP1A1, CYP1A2, MDM2, EGR1, NFKBIZ), further suggesting that genomic outcomes of short-term exposure truly reflect the longer-term process of malignant transformation." (PMID 25058030, 2014). "A growing body of evidence suggests that Egr-1 functions as a tumor suppressor." (PMID 24925061, 2014). "The 11th regulator EGR-1 is a tumor suppressor gene located on q arm of the human chromosome 5." (PMID 25340776, 2014). "The expression of EGR1 and the slight difference between the tumor and non-tumor groups may allude to the possibility of a greater difference in expression between the groups." (PMID 24619124, 2014). "A particular feature of NENs are that they have elevated levels of Ras-related Protein 1 (RAP1) and Serine/threonine-protein kinase B-raf (B-RAF) which in turn activates MAPK thereby enabling the high expression levels of EGR1 leading to increased tumor progression." (PMID 25546138, 2014). "In addition, Egr-1 shRNA suppressed the growth of multicellular tumour spheroids (MTSs), an in vitro tumour model system." (PMID 23152075, 2013). "In addition, Egr-1 is induced by hypoxia and plays a critical role(s) in hypoxia-induced tumour progression, survival, and angiogenesis." (PMID 23152075, 2013). "Likewise, downregulation of EGR1 also correlated with downregulated miR-20b in the normal, benign, and tumor tissues examined (r=0.99, p=0.054)." (PMID 23945289, 2013). "However, studies analyzing the functions of Egr-1 have yielded contradictory findings, with reports of both cytoprotective and proapoptotic functions in tumor cells." (PMID 23717422, 2013). "Thus, Egr-1 is thought to act as a crucial regulator of tumour cell death, growth, invasion, and angiogenesis." (PMID 23152075, 2013). "In fact, re-expression of EGR1 in human tumor cells inhibits neoplastic transformation." (PMID 23505378, 2013). "These included transcription factor EGR1 which is reported to have tumor suppressor properties, genes involved in lymphocyte activation and differentiation such as BCL6, CD4 and SMAD3 and genes TLR3 and TIRAP that are part of the toll-like receptor signaling pathway." (PMID 23072359, 2012). "EGR1 could promote tumor progression, but at the same time, it could serve as a tumor suppressive or proapoptotic regulator." (PMID 23304166, 2012). "Egr1 protects normal cells from transformation by inducing apoptosis or growth arrest upon DNA damage, and its role in chemoresistance and radioresistance in tumor cells is well documented." (PMID 22912725, 2012). "Although its induction is generally transient and greatly dependent on the nature of the various inducers, it appears to be sustained in a high proportion of prostate cancer cell lines and tumors, suggesting that EGR1 stimulates tumor cell growth in certain types of cancer." (PMID 21998680, 2011). "Remarkably, EGR1 can exert effects as either a growth promoter or a tumor suppressor." (PMID 21283769, 2011).
tumor (continued). "Up-regulation of Egr1 expression may result in apparently contradictory activities including mitogenesis, differentiation, tumor suppression, apoptosis, and protection from apoptosis." (PMID 21998680, 2011). "We found that low dose anti-tumour agents up-regulate early growth response 1 (EGR1) expression." (PMID 21283769, 2011). "It has been reported that EGR1 act as either tumour promoting factor or suppressor." (PMID 21283769, 2011). "Following 24 h treatment with these concentrations of anti-tumor drugs, EGR1 was up-regulated." (PMID 21283769, 2011). "We focused on the question whether EGR-1 expression might be related to chemosensitivity of the tumor cells in vitro." (PMID 21366897, 2011). "We next examined the expression of EGR1 following anti-tumour agents treatment." (PMID 21283769, 2011). "We investigated the expression of other tumor-related products, in addition to EGR-1, which might be influencing the response of the tumor cells to the anti-neoplastic treatment." (PMID 21366897, 2011). "Clearly, the topic of EGR1's activity as a tumor suppressor or oncogene remains highly debated." (PMID 20426842, 2010). "Our findings also indicate that the function of DR4 and DR5 is regulated separately intracellularly and the Egr-1 status of a tumour may indicate the sensitivity of the tumour towards death receptor agonist therapeutics." (PMID 20087343, 2010). "Another gene expression change that could reduce tumor burden was the 13 fold increased expression of Egr1 mRNA in the CA/CO group." (PMID 20205934, 2010). "The results of our study may shed light on the connection between Egr-1 expression and tumour aggressiveness." (PMID 20087343, 2010). "Secondly, the tumor samples were all Gleason Score 7; so the possibility remains that EGR1 levels might be elevated in higher grade tumor samples." (PMID 20426842, 2010). "Both over- and under-expression of Egr-1 can impede tumor growth." (PMID 19200397, 2009). "Egr-1 expression levels were also significantly correlated to the tumor growth patterns." (PMID 19878561, 2009). "It has been shown that EGR-1 is involved in multiple regulatory pathways in tumor cells." (PMID 22649602, 2009). "We hypothesized that Egr-1 knockout mice might exhibit reduced tumor growth, possibly due to a reduced capacity to respond to angiogenic signals from a growing tumor." (PMID 19200397, 2009). "Egr-1 is a zinc-finger transcription factor that is inducible by radiation, serum, shear stress, and other stimuli in a variety of cell types, including tumor cells." (PMID 19200397, 2009). "In addition, our analysis of NGF production and the TF Egr1 suggest that the production of growth factors in the tumor tissue represents one mechanism whereby a distant tumor can alter the transcriptome of the salivary gland and hence the saliva." (PMID 19517020, 2009). "It is unknown if EGR1 promotes or suppresses tumor growth in ccRCC." (PMID 39866235, 2025). "Additionally, IR has been reported to induce Egr1 in tumor-derived cells." (PMID 36979689, 2023). "Hence, Egr-1 overexpression has been found to suppress tumor growth in several forms of cancer." (PMID 37046823, 2023). "Early growth response 1 (EGR-1) could involve regulating tumor development in ESCC cells." (PMID 36233659, 2022). "Notably, the role of EGR1 in tumor formation is controversial in diseases and conditions." (PMID 35883603, 2022). "While the role of these transcription factors in a stress-inducible state likely differs from their role in untreated tumors, this result demonstrates that NACT-induced ATF3 and EGR1 may also have very different, unique roles within the tumor microenvironment in a post-NACT setting as well." (PMID 36131935, 2022). "In this study, EGR-1 was hypothesized to play a vital role in tumor suppression in ESCC cells." (PMID 36233659, 2022).
tumor (continued). "Egr-1 interactions with these genes and microRNAs may be important in tumor progression." (PMID 36207572, 2022). "However, some research supports our hypothesis that EGR-1 may be a tumor suppressor in many types of cancer." (PMID 36233659, 2022). "Finally, Klf4 and Egr1 levels were lower in the CTCs containing Parsortix-isolated samples, while Dusp10 and Pmepa1 higher levels in these samples could indicate tumor presence." (PMID 35153760, 2021). "Moreover, miR-377-3p mediated EGR1 downregulation facilitates cell malignant transformation and tumor formation by regulating the Wnt/β-catenin pathway, suggesting an important role of the miR-377-3p/EGR1 axis in the malignant transformation of lung tumorigenesis induced by environmental carcinogen." (PMID 34497759, 2021). "Moreover, EGR1 overexpression reduced the cell migration ability and xenograft tumor growth." (PMID 34497759, 2021). "Consequently, EGR1 may control β-catenin expression and enhance tumor invasion and metastasis, but the specific mechanism is yet to be revealed." (PMID 33842351, 2021). "We hypothesized that EGR1 could suppress tumor progression in the thyroid." (PMID 33477921, 2021). "Thus, several studies have indicated that EGR1 is a tumor suppressor in CRC." (PMID 33346749, 2020). "EGR1, OSBPL8 (encoded by the gene KIAA1451), FAM171A2, FGD6, and CEP131 showed particularly high or largely exclusive staining in stromal cells, supporting the notion that indeed the expression profile of CAFs drives tumor classification in our random forest model." (PMID 31505876, 2019). "EGR1 may exert different biological effects in different tumours." (PMID 31515938, 2019). "The role of the transcription factor EGR1 in tumour development and progression is dependent upon the sum of the functions of the genes that it regulates, but it has been shown to up-regulate multiple tumour suppressor genes to inhibit cell growth, proliferation and metastasis." (PMID 30566430, 2018). "However, other studies showed that activation of EGR1 induced tumor cell apoptosis." (PMID 27442508, 2016). "Indeed, EGR1 knockdown attenuated the KLF12-induced growth of tumor cell populations." (PMID 27442508, 2016). "Indeed, KLF12 promotes tumor growth by directly activating early growth response protein 1 (EGR1)." (PMID 27442508, 2016). "EGR-1 may act as either a tumor promoter or suppressor, depending on the type of tumor." (PMID 26573568, 2015). "However, sustained expression of Egr-1 suppresses tumor growth and neovascularization." (PMID 25502753, 2014). "Our findings thus demonstrate for the first time that EGR1 is a key player in the transcriptional control of miR-20b, and miR-20b may in turn function as an oncogene by contributing to breast tumorigenesis via tumor suppressor targeting." (PMID 23945289, 2013). "We were therefore interested in whether chemotherapy agents might similarly alter the expression of inducible invasion-related genes, and thereby potentially alter tumor invasiveness, and found that anti-tumour agents increased the expression of EGR1, and EGR1 decreased that of uPA and uPAR." (PMID 21283769, 2011). "Modifications that affect Egr1 expression or stability could significantly impact growth factor regulated gene expression and small changes in Egr1 expression levels can have significant impact on cells survival and proliferation of different tumor cell lines." (PMID 21998680, 2011). "However, reduction of Egr-1 levels through use of a DNAzyme also resulted in slower tumor growth." (PMID 19200397, 2009). "Finally, we found that Egr-1 expression was significantly correlated to tumor grade." (PMID 19878561, 2009).
tumor (continued). "This also emphasizes that Egr-1 may play a role in tumor progression." (PMID 19878561, 2009). "In our study, we observed a marked upregulation of EGR1 mRNA under hypoxic conditions in HCC cells, supporting its context-dependent regulatory function during tumor adaptation to stress." (PMID 41356200, 2026). "CONCLUSION: Endothelial cell-derived IGFBP7 suppresses CRC progression via the EGR1/TGF-β1 pathway, while VAPA-mediated lysosomal degradation limits its tumor-suppressive function." (PMID 41692778, 2026). "To further confirm the role of EGR1 in tumor growth, we established nude mouse subcutaneous xenograft models using Cas13a-mBN-MLS-mediated mitochondria-specific EGR1 targeting and shRNA-mediated cellular EGR1 knockdown." (PMID 41356200, 2026). "CDK6 specifically regulates the transcription of tumor-related genes such as vascular endothelial growth factor-A (VEGF-A) and early growth response gene-1 (EGR1), thereby promoting the transcription of genes from G1 to S phase." (PMID 39944826, 2025). "Specifically, hepatocytes at the tumor periphery predominantly expressed TFs such as ILF2, ATF7, and RFXANK, while those in the tumor core were enriched for KLF4, EGR1, and HES5." (PMID 40474968, 2025). "Further, immunohistochemistry of 4-HNE and MDA, and double immunofluorescence labelling of EGR1 and MDA, demonstrated decreased levels of these markers and EGR1 in APA tumor tissues relative to the adjacent cortex." (PMID 39826326, 2025). "The increased autophagy activity induced by highly expressed autophagy-related genes including ATG4B decreases the expression of SESN3, a novel tumor-suppressor in T-ALL through autophagy-mediated protein degradation and EGR1-regulated transcription." (PMID 41275290, 2025). "When focusing on regulatory patterns, we found that CAFs displayed distinct cell type-specific TFs alongside shared TFs widely involved in carcinogenesis, including various tumor promoters or tumor suppressors, such as KLF4, NFIA, TCF21, NFKB1, and EGR1." (PMID 39872221, 2025). "EGR1 can modulate the expression of growth factors, such as IGF2 and TGF-β1, as well as that of NAB2, and is believed to act either as an oncogene or tumor suppressor depending on the cellular context." (PMID 40875449, 2025). "For example, EGR1 has been shown to suppress β-catenin levels via the PTEN-AKT-GSK3β signaling pathway, thereby modulating tumor invasion and metastasis." (PMID 40519297, 2025). "Mechanistically, PLCH1 silencing downregulated early growth response 1 (EGR1) expression by suppressing the extracellular signal-regulated kinases 1 and 2 (ERK1/2) signaling pathway, impairing tumor cell proliferation." (PMID 40519297, 2025). "These experimental findings provide compelling evidence of the critical roles of WTAP, EGR1, and PTEN in regulating tumor growth and maintaining stem cell-like characteristics in EC." (PMID 39044249, 2024). "A comparison of EGR1, FOS, IER2, JUN, KLF6, MYC, and FOSL2 gene expression in 481 tumor samples revealed that individual tumors vary substantially in the expression of all analyzed genes." (PMID 39436655, 2024). "The expression of fibrotic genes EGR1, JUND, KLF2 and TAGLN also decreases in tumour samples (PH4 module)." (PMID 38157373, 2023). "To further confirm the relevance of modulating EGR1 to reduce TFEB-driven oncogenic properties, we developed 3D cultures from HeLa-FLCN KO cells to mimic the tumor microenvironment better." (PMID 36888606, 2023). "Through the PI3K/AKT/EGR-1 pathway, CD74 enhances tumor invasion and promotes neuroplasticity by increasing GDNF secretion, thereby facilitating tumor invasion." (PMID 38099290, 2023).